LPL (lipoprotein lipase)
Description:
Key enzyme in triglyceride metabolism. Catalyzes the hydrolysis of triglycerides from circulating chylomicrons and very low density lipoproteins (VLDL), and thereby plays an important role in lipid clearance from the blood stream, lipid utilization and storage. Although it has both phospholipase and triglyceride lipase activities it is primarily a triglyceride lipase with low but detectable phospholipase activity. Mediates margination of triglyceride-rich lipoprotein particles in capillaries. Recruited to its site of action on the luminal surface of vascular endothelium by binding to GPIHBP1 and cell surface heparan sulfate proteoglycans.
Synonyms: LIPD; HDLCQ11
Tractability: Small molecule: a structure with a bound ligand is known; a high-quality ligand is known; it belongs to a druggable protein family. Antibody: UniProt places it where antibodies can reach, with high confidence; its Gene Ontology location is reachable by antibodies, with high confidence; UniProt predicts a signal peptide or a membrane-spanning region. PROTAC: ubiquitination databases record sites on it; its protein half-life has been measured; a small molecule that binds it is known.
Target class: Enzyme; Hydrolase
Gene: Protein-coding gene on chromosome 8 (19,901,717 to 19,967,267, forward strand). Ensembl gene ENSG00000175445.
Subcellular location: Cell membrane; Secreted; Secreted, extracellular space, extracellular matrix
Subcellular location (Human Protein Atlas): Vesicles; Predicted to be secreted
Pathways (Reactome):
Transport of small molecules: Assembly of active LPL and LIPC lipase complexes; Chylomicron remodeling
Developmental Biology: Transcriptional regulation of white adipocyte differentiation
Gene expression (Transcription): MLL4 and MLL3 complexes regulate expression of PPARG target genes in adipogenesis and hepatic steatosis
Sensory Perception: Retinoid metabolism and transport
Gene Ontology:
Molecular function: apolipoprotein binding; calcium ion binding; heparan sulfate proteoglycan binding; heparin binding; lipoprotein lipase activity; lipoprotein particle binding; phospholipase A1 activity; protein binding; protein homodimerization activity; signaling receptor binding; triacylglycerol lipase activity; phospholipase activity; protein-membrane adaptor activity; carboxylic ester hydrolase activity; lipase activity
Biological process: cholesterol homeostasis; chylomicron remodeling; fatty acid biosynthetic process; fatty acid metabolic process; low-density lipoprotein particle mediated signaling; positive regulation of adipose tissue development; positive regulation of chemokine production; positive regulation of cholesterol storage; positive regulation of fat cell differentiation; positive regulation of inflammatory response; positive regulation of macrophage derived foam cell differentiation; positive regulation of triglyceride transport; triglyceride catabolic process; triglyceride homeostasis; triglyceride metabolic process; very-low-density lipoprotein particle remodeling; cellular response to fatty acid; cellular response to nutrient; high-density lipoprotein particle remodeling; phospholipid metabolic process; positive regulation of chemokine (C-X-C motif) ligand 2 production; positive regulation of interleukin-1 beta production; positive regulation of interleukin-6 production; positive regulation of lipid storage; positive regulation of tumor necrosis factor production; and 5 more
Cellular component: catalytic complex; extracellular region; plasma membrane; cell surface
Genetic constraint (gnomAD): Loss-of-function variants: 41 observed, 49.47 expected, observed/expected ratio (o/e) 0.83, 90% interval 0.64 to 1.08. The upper end of that interval is the gene's LOEUF score, 1.08, which puts it in group 4 of 6, group 1 being the genes least tolerant of losing a copy. Missense variants: 631 observed, 606.79 expected, observed/expected ratio (o/e) 1.04, 90% interval 0.97 to 1.11. Synonymous variants: 241 observed, 227.07 expected, observed/expected ratio (o/e) 1.06, 90% interval 0.95 to 1.18.
Homologues: Orthologues: chimpanzee LPL (99% identical), macaque LPL (99% identical), mouse Lpl (93% identical), rat Lpl (92% identical), pig LPL (92% identical), dog LPL (92% identical), rabbit LPL (85% identical), guinea pig LPL (83% identical), tropical clawed frog lpl (71% identical), zebrafish lpla (59% identical), zebrafish lplb (56% identical), Drosophila melanogaster CG6296 (24% identical), and 14 more. Paralogues in human: LIPG (45% identical), LIPC (44% identical), LIPH (27% identical), PNLIPRP1 (27% identical), PNLIP (27% identical), PNLIPRP2 (26% identical), LIPI (26% identical), PNLIPRP3 (24% identical), PLA1A (24% identical).
Diseases named in the same sentence as LPL in open-access papers:
LPL is named in the same sentence as 340 diseases in open-access papers, as found by Europe PMC text mining. Sharing a sentence is not in itself a finding about the gene and the disease. The quoted sentences say what the papers report.
hypertriglyceridemia (422 papers, 2002 to 2026). A laboratory test result indicating elevated triglyceride concentration in the blood. "Marked hypertriglyceridemia can accompany insulin deficiency through increased lipolysis and reduced lipoprotein lipase activity." (PMID 41562825, 2026). "some studies propose that TAC causes a decline in the activity and plasma concentration of lipoprotein lipase, leading to hypertriglyceridemia, which is an independent risk factor for AP." (PMID 40701574, 2025). "Cyp7b1-deficient rats are resistant to postprandial hypertriglyceridemia, a common feature with mice expressing human lipoprotein lipase and Apoc3-deficient mice." (PMID 41465421, 2025). "Genetic testing confirmed familial hypertriglyceridaemia with a pathogenic variant in the lipoprotein lipase gene." (PMID 41437989, 2025). "One of the genes with heterozygous variant implicated in familial hypertriglyceridaemia is the LPL gene, affecting the function of LPL." (PMID 41437989, 2025). "In a cohort of patients with severe hypertriglyceridaemia in Brazil, the most frequent variant in LPL gene was the c.701C>T (p.Pro234Leu), which was also the one detected in our patient." (PMID 41437989, 2025). "Mutations in LMF1 are typically found in a homozygous or compound heterozygous state and lead to a deficiency in LPL activity, resulting in severe hypertriglyceridemia." (PMID 40142634, 2025). "Lastly, the hyperchylomicronemic phenotype is defined by extreme hypertriglyceridemia due to impaired clearance of chylomicrons, typically caused by genetic defects in lipoprotein lipase (LPL) or its co-factors, such as ApoC-II and GPIHBP1." (PMID 41346943, 2025). "Both quantitative and qualitative defects in LPL are associated with hypertriglyceridemia in the form of familial chylomicronemia." (PMID 39940794, 2025). "Disabling trans-capillary LPL transport by inhibitory GPIHBP1 autoantibodies also causes hypertriglyceridemia." (PMID 39814316, 2025). "APOA5 and LPL LOF variants are associated with hypertriglyceridemia yet few missense variants are associated with these clinical phenotypes." (PMID 40473624, 2025). "Familial chylomicronemia syndrome (FCS) is a rare genetic disorder associated with impaired LPL function, resulting in severe hypertriglyceridemia and recurrent acute pancreatitis." (PMID 41180755, 2025). "Mutations in the LPL gene can lead to LPL deficiency, a condition marked by severe hypertriglyceridemia due to impaired clearance of TRLs." (PMID 38288833, 2024). "A recent study revealed that patients with severe hypertriglyceridemia (STG) having a history of AP had a higher frequency of the rare variants in the LPL gene and all the LPL molecular regulating genes." (PMID 38530959, 2024). "Preterm infants have lower levels of lipoprotein lipase and as a result are at an increased risk for hypertriglyceridemia during periods of parenteral nutrition (PN)." (PMID 39394360, 2024). "When there is decreased LPL activity, the result is hypertriglyceridemia, a condition associated with adverse health outcomes." (PMID 38279305, 2024). "Elevated levels of interleukin 1 and 6 and tumor necrosis factor α cause fever and hypertriglyceridemia by inhibiting lipoprotein lipase, and the secretion of activated macrophages causes high ferritin levels." (PMID 39055122, 2024). "LPL activity is regulated by the actions of several regulatory proteins, which have been linked to hypertriglyceridemia, remnant generation, and CVD risk." (PMID 38879166, 2024). "ApoCII is an essential cofactor for LPL, and while apoCII deficiency is associated with reduced LPL activity and marked hypertriglyceridemia, excess levels have also been inconsistently associated with elevated TG levels." (PMID 38879166, 2024). "Alterations in LPL were associated with impaired clearance of plasma TG, which was associated with hypertriglyceridemia." (PMID 38973609, 2024).
hypertriglyceridemia (continued). "Here, we report our experience managing two unrelated infants consecutively diagnosed with hypertriglyceridemia‐induced acute pancreatitis caused by LPL deficiency." (PMID 38974610, 2024). "This study reports a novel occurrence of such rare biallelic LPL variants in a Chinese patient with hypertriglyceridemia-induced acute pancreatitis (HTG-AP) during pregnancy and provides an in-depth functional characterization." (PMID 38561841, 2024). "Suppression of adipose LPL following PAR2 expression was associated with hypertriglyceridemia and was reversed in Par2–/– mice." (PMID 38973609, 2024). "Human obesity increases adipose PAR2 expression, which is associated with downregulation of LPL expression and hypertriglyceridemia." (PMID 38973609, 2024). "This, in turn, leads to hypertriglyceridemia, as fat and muscle tissues are deficient in lipoprotein lipase." (PMID 39759497, 2024). "HLH syndrome, acquired lipoprotein lipase inhibitors, medication side effects, or acute liver failure are the underlying mechanisms thought to contribute to COVID-19-induced hypertriglyceridemia." (PMID 38979030, 2024). "ApoC2 is an activator for LPL activity, and decreased apoC2 activities are inversely associated with hypertriglyceridemia in humans." (PMID 39234305, 2024). "Homozygous or compound heterozygous LPL variants cause autosomal recessive familial chylomicronemia syndrome (FCS), whereas simple heterozygous LPL variants are associated with hypertriglyceridemia (HTG) and HTG-related disorders." (PMID 37568214, 2023). "Partial loss of LPL function due to monoallelic (simple heterozygous) LPL variants is associated with hypertriglyceridemia (HTG)." (PMID 37568214, 2023). "This hyperlipidemia can be a manifestation of hereditary hypertriglyceridemia due to a defect in the genes encoding LPL or its cofactor-apoCII." (PMID 36979789, 2023). "Hypertriglyceridemia caused by P-407 has mainly been attributed to the inhibition of LPL activity in rats and mice as previously reported." (PMID 36814487, 2023). "According to our statistical analysis, the H+H+ LPL-Hind lll polymorphism was the strongest genetic marker of susceptibility to severe hypertriglyceridemia, which was similar to the results of other studies." (PMID 37954769, 2023). "Active LPL is needed to prevent hypertriglyceridemia, which is a risk factor for cardiovascular disease (CVD)." (PMID 37142573, 2023). "Hypertriglyceridemia increases the risk for macrosomia due to factors such as insulin resistance caused by elevated triglycerides along with reduced lipoprotein lipase function." (PMID 38260157, 2023). "ApoC2 is well known to be a critical LPL activator required for TG hydrolysis, as evidenced by the fact that ApoC2 deficiency causes severe hypertriglyceridemia." (PMID 37666362, 2023). "LPL deficiency is the primary differential diagnosis to consider in the case of severe hypertriglyceridemia, i.e., TGs above 20 mmol/L." (PMID 37630727, 2023). "We suspect that the ANGPTL3/8 mAb, by increasing intracapillary LPL levels, will be highly effective in treating hypertriglyceridemia in patients with APOA5 deficiency." (PMID 37824203, 2023). "Why apolipoprotein AV (APOA5) deficiency causes hypertriglyceridemia has remained unclear, but we have suspected that the underlying cause is reduced amounts of lipoprotein lipase (LPL) in capillaries." (PMID 37824203, 2023). "Known LPL mutations that lead to hypertriglyceridemia localize to the end of the pore and cause defective substrate hydrolysis." (PMID 37142573, 2023). "Loss-of-function variants in the LPL gene are associated with hypertriglyceridemia (HTG) and HTG-related diseases." (PMID 37550668, 2023). "The combination of LMF1 and LPL gene mutations significantly decreased LPL mass, which contributes to severe hypertriglyceridemia." (PMID 35368694, 2022). "In diabetes, however, lipoprotein lipase cannot be sufficiently activated due to insulin deficiency resulting in hypertriglyceridaemia." (PMID 36297315, 2022).
hypertriglyceridemia (continued). "A recent study also shows that high levels of both apoE and apoA2 were strongly inversely associated with the ability of lipoprotein lipase to hydrolyze TG in plasma—the process which plays a key role in hypertriglyceridemia development." (PMID 35745122, 2022). "Glybera®, the first gene therapy product targeting atheroscletosis, is an AAV1 vector carrying an intact copy of LPL aimed at reversing the severe hyper-triglyceridemia-causing LPL deficiency." (PMID 35371605, 2022). "The most severe type of HTG is primary (or hereditary) hypertriglyceridemia, linked to pathogenic genetic variants in LPL, APOC2, LMF1, and APOA5 genes." (PMID 35741823, 2022). "Lipoprotein lipase, which hydrolyzes triglycerides, is activated by insulin during metabolism, but insulin shortage causes insulin to be inactivated, resulting in hypertriglyceridemia." (PMID 36235206, 2022). "The influx of TRL-derived FFAs in metabolic tissues appears within minutes after injection of labeled chylomicron/VLDL-TG and is largely dependent on LPL activity; loss-of-function GPIHBP1 or LPL mutations lead to severe hypertriglyceridemia." (PMID 35289308, 2022). "Loss-of-function mutations in LPL caused type I hyperlipoproteinemia in human, characterized by very severe hypertriglyceridemia." (PMID 36712873, 2022). "Various GPIHBP1 mutations have been found to prevent GPIHBP1 from binding LPL, resulting in invalid processing of TG and severe hypertriglyceridemia." (PMID 35741760, 2022). "Defective LPL can cause the accumulation of triglyceride-rich chylomicrons and very low-density lipoproteins and further lead to severe hypertriglyceridemia." (PMID 35923617, 2022). "The clinical significance of LPL-processing factors is highlighted by the fact that LMF1 and GPIHBP1 genetic variants are associated with compromised LPL function and severe hypertriglyceridemia (HTG)." (PMID 35911520, 2022). "Another suggested mechanism is a reduced enzymatic activity of LPL, a key enzyme in the removal of triglyceride-rich lipoproteins from plasma, reducing clearance and consequently causing hypertriglyceridaemia." (PMID 36009482, 2022). "Recently, emerging evidence has shown that LPL overexpression or increases in LPL activity can reduce plasma TG content and increase high-density lipoprotein cholesterol (HDL-C) levels; however, deficiency of LPL activity leads to hypertriglyceridemia." (PMID 36293338, 2022). "In Burmese cats with postprandial hypertriglyceridemia, lipoprotein lipase (LPL) deficiency and elevated very-low-density lipoprotein (VLDL) concentrations have been observed." (PMID 36248900, 2022). "LPL is associated with the hydrolysis triglyerides and alteration in the normal physiology can lead to hypertriglyceridemia." (PMID 35241081, 2022). "Type I hyperlipoproteinemia, characterized by severe hypertriglyceridemia, is caused mainly by loss-of-function mutation of the lipoprotein lipase (LPL) gene." (PMID 35923617, 2022). "The importance of LPL for systemic lipid metabolism is demonstrated by the observation that LPL deficiency in humans and mice leads to massive hypertriglyceridemia." (PMID 35422714, 2022). "For severe hypertriglyceridemia, pathogenic variants in genes LPL, APOA5, APOC2, GPIHBP1, and LMF1, associated with hyperlipidemia should be considered." (PMID 36051701, 2022). "Although the individual distributions of all the three ANGPTLs are different, these proteins, which are intricately regulated, appear to inhibit LPL activity and cause hypertriglyceridemia, the dynamics of which cannot be explained via a central dogma." (PMID 34293055, 2021). "Familial chylomicronemia, mainly caused by lipoprotein lipase deficiency due to biallelic pathogenic variants in the LPL gene is the most common genetic cause of severe hypertriglyceridemia." (PMID 33879184, 2021).